EIF4E (eukaryotic translation initiation factor 4E)
Diseases named in the same sentence as EIF4E in open-access papers (continued):
Sharing a sentence is not in itself a finding about the gene and the disease.
tumor (continued). "As an alternative strategy, inhibiting eIF4E expression with antisense oligonucleotides (AON) has given promising results in suppressing tumor growth in vivo." (PMID 22666083, 2012). "Antisense RNA-mediated reduction of eIF4E in breast, head and neck cancer cells was also shown to suppress tumour formation, growth and metastasis." (PMID 22392765, 2012). "Since then, numerous studies have reported overexpression of eIF4E in different tumor types (e.g., breast, prostate, gastric colon, lung, skin, and lymphomas)." (PMID 22666083, 2012). "The in vivo effects of compound 4EGI-1 on the formation of eIF4F complex were investigated by pulling-down eIF4E from tumor lysates by 7-methylguanosine diphosphate (M7GDP)-Sepharose affinity chromatography followed by WB analysis of eIF4E, eIF4G and 4E-BP1." (PMID 22935625, 2012). "The tumor itself, the surgical margins, and even the histologically normal epithelium in the margins were all shown to overexpress eIF4E." (PMID 21513566, 2011). "The requirement for eIF4E hyperactivity in AKT-driven tumours has been further substantiated by recent studies." (PMID 21772331, 2011). "Thirty-six patients (55%) with microscopic tumor-free margins had eIF4E expression in the basal cell layer of the margin." (PMID 21513566, 2011). "This study showed that TORC1-dependent eIF4E hyperactivation (via 4EBP1 inactivation) was essential for tumor growth, whereas S6K activation was dispensable." (PMID 20657741, 2010). "Here, mice that intravenously received antisense oligonucleotides showed significant reduction of eIF4E expression and suppressed tumor growth." (PMID 20049173, 2009). "We had selected tumor samples that showed a wide range of eIF4E protein expression by western blot which was significantly higher than the normal tissues." (PMID 19134194, 2009). "Because of this, the specific suppression of eIF4E activity can turn out to be very useful in inhibiting tumor progression." (PMID 22649602, 2009). "Some studies report that eIF4E is overexpressed in almost 100% of tumors of the breast, head and neck, and colon." (PMID 20049173, 2009). "Other known PI3K and dMyc-dMax target genes that promote proliferation include ribosomal proteins and translation regulators, such as eIF4E, which is highly expressed in dEGFRλ;dp110CAAX glia and required for neoplasia." (PMID 19214224, 2009). "Overexpression of eIF4E in >5% of the basal layer of histologically tumor-free surgical margins of HNSCC patients predicted a significantly increased risk of recurrence." (PMID 20049173, 2009). "eIF4E is often overexpressed in carcinoma cells as compared to equivalent normal epithelium in many tumour types including breast, lung and colon." (PMID 19367274, 2009). "In xenograft mouse models, studies had shown that genetically reducing the levels of eIF4E protein by antisense RNA substantially impaired tumour growth." (PMID 20049173, 2009). "The ratios of p4E-BP1 to total 4E-BP1 and of eIF4E to 4E-BP1 have been shown to correlate with high tumour grade, but their relationships with survival were not examined." (PMID 19367274, 2009). "Binding sites for many of the microRNAs reported to have tumor suppressive effects are more likely to be under-represented in the mRNAs most sensitive to eIF4E-dependent translational upregulation." (PMID 19290046, 2009). "One tumour contained elevated eIF4E and several biochemical characteristics closely matched the one cell line with eIF4E overexpression." (PMID 15956968, 2005). "Levels of eIF4E were generally higher in the matched normal samples than in the tumours, with the exception of tumour #12 that had substantially increased eIF4E (compare lanes 23 and 24)." (PMID 15956968, 2005). "Increased eIF-4E mRNA levels were detected in the tumours (P < 0.0001) that correlated with VEGF mRNA (P = 0.0002), implying co-regulation of these genes." (PMID 9649123, 1998).
tumor (continued). "Furthermore, our findings elucidate that eIF4E‐EVs promote tumor formation by inducing the accumulation of cholesterol in macrophages via 3‐hydroxy‐3‐methyl‐glutaryl‐coenzyme A reductase (HMGCR), resulting in an immunosuppressive phenotype in the TME." (PMID 40820860, 2025). "In addition, a more established research model shows that eIF4E3 competes with eIF4E for the same transcriptional pool to inhibit the oncogenic capacity of eIF4E to drive tumour development." (PMID 41208200, 2025). "Therefore, targeting the eIF4E complex through competitive m7G cap inhibitors is also essential for anti‐tumour drug development." (PMID 41208200, 2025). "The 5′ UTR of basic fibroblast growth factor-2 (bFGF-2) contains various higher-order structures, with a GC-rich segment that is unraveled in tumor cells due to the overexpression of translation initiation factor 4E (eIF4E), resulting in increased translation of downstream genes." (PMID 40723232, 2025). "Moreover, it has been shown that eIF4E knockout mice not only maintain normal physiology, but also have significant tumour suppression effects." (PMID 40579921, 2025). "Importantly, eIF4E activity is a key target of oncogenic signals, which promote addiction to hyperactive eIF4E-dependent translation in tumor cells." (PMID 39869680, 2025). "However, we discovered that tumors still developed in mice overexpressing 4EBP1A4, probably due to compensatory mechanisms that led to the resistance to 4EBP1/eIF4E pathway inhibition over the long-term course of tumor growth." (PMID 39325536, 2024). "This work proposes that EBV‐positive GC patients with mTOR/eIF4E hyperactivation may benefit from anti‐tumor immunotherapy." (PMID 38994917, 2024). "The role of eIF4E in neoplasia is very well studied and established." (PMID 39409166, 2024). "Indeed, examples of translational control involving the ternary complex member eIF2-alpha and subunits of the translation initiation complex eIF4F, particularly eIF4E, have been shown to regulate tumor immune escape." (PMID 37747887, 2023). "In addition, unlike eIF4E, which is an essential protein for all cells, p-eIF4E occurs only in tumor cells or virus-infected cells." (PMID 37243186, 2023). "In addition, the exact mechanism of tumor occurrence, development, and metastasis mediated by eIF4E is still poorly understood, and the relationship between eIF4E and tumors should be paid attention to and further studied." (PMID 37601696, 2023). "eIF4E mRNA and protein expression increases with the increase of tumor grade." (PMID 36994107, 2023). "It has been demonstrated that elevated eIF4E levels in BC promote tumor progression." (PMID 37217473, 2023). "Overexpression of eIF4E promoted tumor cell and HUVEC tube formation." (PMID 37217473, 2023). "This helps to gain a deeper understanding of the overexpression of eIF4E in tumor cells." (PMID 37601696, 2023). "The overexpression of eIF4E at the incisal edge would increase the probability of tumor recurrence." (PMID 37601696, 2023). "The expression of eIF4E in tumor tissue is significantly higher than that in normal tissue." (PMID 37601696, 2023). "This expression characteristic of eIF4E makes it a potential tumor detection indicator." (PMID 37601696, 2023). "Therefore, eIF4E is a marker of tumor progression, malignant transformation, metastasis, and poor prognosis." (PMID 37601696, 2023). "Similarly, analyses of TCGA dataset also indicated that eIF4E expression levels were positively correlated with that of DLAT in NSCLC tumor tissues." (PMID 35869499, 2022).
tumor (continued). "Furthermore, expressions of eIF4E and p-4EBP1 were significantly correlated with tumor recurrence or recurrence-free survival." (PMID 36555391, 2022). "Furthermore, the CPT single treatment also significantly inhibited the activities of STAT3 and eIF4E signalling pathways in tumour tissues." (PMID 34214017, 2021). "Therefore, the authors postulated that significant molecular changes occur in advance of any histological signs of tumor recurrence, thereby identifying eIF4E as a highly sensitive marker for HNSCC growth." (PMID 34344911, 2021). "eIF4E may act as an essential regulator of tumor macrophage infiltration and may participate in macrophage M2 polarization." (PMID 34876062, 2021). "Moreover, the inhibition of eIF4E in human tumor xenografts significantly induced apoptosis and suppressed tumor growth." (PMID 33460399, 2021). "Among them, SNHG12, FTX, SNHG5 and ZNFX1-AS1 were found to be associated with translation machinery via eIF4E-RNA-binding motifs (but not the cap-binding domain) in MCL tumor cells." (PMID 34502399, 2021). "Therefore, according to the differences in BRCA subtypes, tumor stages and lymph node metastasis, the expression of eIF4E can be used as a prognostic biomarker in BRCA." (PMID 34876062, 2021). "In BRCA in general, eIF4E expression was significantly correlated with tumor purity (r = 0.134, P = 2.2e-05), CD8+ T cells (r = 0.268, P = 1.5e-17), macrophages (r = 0.237, P = 5.1e-14), neutrophils (r = 0.161, P = 6.1e-07) and dendritic cells (r = 0.067, P = 3.9e-02)." (PMID 34876062, 2021). "In addition, we used the Kaplan–Meier database to evaluate the relationship between the expression of eIF4E in a range of tumor types and prognosis." (PMID 34876062, 2021). "High expression of eIF4E may regulate macrophage infiltration into the tumor and may participate in macrophage M2 polarization." (PMID 34876062, 2021). "Activation of mTORC1 causes phosphorylation of 4E-BPs (on T37, T46 and S65 of 4E-BP1), leading to dissociation of 4E-BPs from eIF4E to allow eIF4F assembly and augment cap-dependent translation of a subset of cellular mRNAs important for tumorigenesis and maintenance of tumor growth." (PMID 34408976, 2021). "Finally, interaction network and functional enrichment analysis revealed that eIF4E was mainly involved in tumor-related pathways, including the cell adhesion molecule pathway and the JAK-STAT signaling pathway." (PMID 34876062, 2021). "Polysome-profiling of MEFs isolated from knock-in mouse and PCa cell lines treated with CGP57380 allowed the identification of MNK/eIF4E-dependent mRNAs as VEGFC, BIRC2, MMP3, and NFKBIA, pro-tumorigenic proteins whose decrease was associated with tumor development resistance." (PMID 32340135, 2020). "For example, in 1990, the discovery that eIF4E overexpression could drive tumor initiation has led to the development of strategies to decrease its expression." (PMID 32241281, 2020). "In addition, phosphorylated eIF4E-driven survival of neutrophils is required for their ability to accumulate in the tumor and promote metastasis." (PMID 32731503, 2020). "eIF4E in tumor has therefore become an anticancer drug target." (PMID 32708122, 2020). "When eIF4E is overexpressed, it can selectively affect the translation rate of some certain proteins, thus inducing cell proliferation and promoting the antiapoptosis, invasion, recurrence, and metastasis of tumor cells." (PMID 33489719, 2020). "Hence, ribavirin was considered to be a remarkable inhibitor of primary tumor growth in an eIF4E-dependent manner, in vivo and in vitro." (PMID 32708122, 2020).
tumor (continued). "Knock-down of EIF4E results in suppression of the tumorigenic and angiogenic properties of the FaDu cell line manifested by loss of capacity to grow in soft agar, reduced expression of angiogenic factors (FGF-2 and VGF), and loss of tumor growth in nude mice." (PMID 31010087, 2019). "For example, eIF4E is involved in the regulation of genes coding for proto-oncogene proteins like c-myc and cyclin D1 which are involved in cell proliferation and promote tumor growth." (PMID 31795417, 2019). "Furthermore, the PHB-ligand FL3 determined anti-tumor activities in vitro and in vivo that were associated with inhibition of ERK/MNK/eIF4E signaling pathways and AKT expression." (PMID 31684984, 2019). "Inhibition by an eIF4E siRNA blocked the effect, inhibiting tumour cell growth in vitro." (PMID 30923340, 2019). "However, multiple mouse studies have demonstrated that phosphorylated eIF4E is involved in increasing the translation rates of a subset of mRNAs that play a significant role in tumour development." (PMID 31118010, 2019). "Moreover, the underlying mechanism of lower expression levels of p-PI3K and p-eIF4E in patients with tumor recurrence must be investigated." (PMID 31756179, 2019). "The expression levels of p-eIF4E protein significantly differed in pT stage and pN (p < 0.001 and p = 0.030, respectively), whereas p-eIF4E protein was expressed at comparable levels in tumours of different Fuhrman grade, sarcomatoid differentiation, coagulative necrosis, and MVI." (PMID 31258849, 2019). "eIF4E is phosphorylated mainly by MNK2a in tumour specimens and cell lines." (PMID 31258849, 2019). "In some cells, MAPK-interacting kinases (MNK1/2), phosphorylate eIF4E and enhance tumor growth." (PMID 31878201, 2019). "Immunostaining of HCC patient tumor tissues revealed a varying ratio of eIF4E/4E-BP1 expression." (PMID 28881582, 2017). "eIF4E plays a major role in the regulation of tumor growth, invasion and metastasis." (PMID 29254159, 2017). "Our in vitro studies suggest that EPO-mediated activation of eIF4E may play an important role in tumor cell proliferation." (PMID 28415825, 2017). "Furthermore, hyperactivation of eIF4E as the result of 4EBP1 inhibition is required for mTOR-mediated tumor development." (PMID 28187001, 2017). "Our work adds β-catenin to the list of eIF4E-targeted tumor promoting genes." (PMID 27926520, 2017). "The effect of eIF4E on tumor has been investigated by studying the mechanisms of MNKs." (PMID 28878291, 2017). "Furthermore, 4EBP1 and p70S6K1, which are regulated by growth factor-mediated mTOR signaling, control tumor development and progression through eIF4E-mediated cap-dependent translation of tumor promoting genes, such as survivin, HIF-1α, cyclin D1, and c-Myc." (PMID 28961193, 2017). "MNK1/2 deficiency presents a non-detectable level of eIF4E phosphorylation, delays tumor development, and decreases in vitro oncogenic activity of glioma cells." (PMID 28878291, 2017). "Thus, indicating that MNK2 promote NSCLC tumor growth and progression via 4EBP1/eIF4E and ERK/eIF4E pathway." (PMID 28878291, 2017). "This deregulation could be attributed to eukaryotic translation initiation factor 4E (EIF4E), an oncogene that regulates the translation of a specific subset of tumour-promoting mRNAs." (PMID 26646586, 2016). "Phosphorylated eIF4E was expressed in the cytoplasm of tumor cells." (PMID 27440383, 2016). "In the present study, we observed that the phosphorylated form of eIF4E increased with tumor grade." (PMID 27440383, 2016). "Overexpression of eIF4E leads to enhance the translation of key malignancy-related proteins and enabling tumor growth and chemoresistance in a variety of human malignancies, but whether it has a role in ESCC remains obscure." (PMID 27588477, 2016).
tumor (continued). "Of note, our in vivo results supported the inhibitory activity of 3-AWA on tumor growth and metastasis at as low as 5 mg/kg doses, illustrating moderately less expression of eIF4E/phospho-eIF4E, c-FLIP and elevated FAS expression, which were in accordance with our in vitro studies." (PMID 26728896, 2016). "In contrast, there was no statistical difference between DDP treated and NS treated animals on the effect of tumor growth inhibition in eIF4E overexpressed group, which indicated that increased eIF4E might invalidate DDP anticancer effect (P = 0.3034)." (PMID 27588477, 2016). "Besides, 4EGI-1 induced apoptosis in NPC cells through the DR5-caspase-8 axis on 4E-BP1 and eIF4E dephosphorylation exerting positive influence on their anti-tumor activities." (PMID 26942880, 2016). "Activation of both MYC and eIF4E have been found in human tumor cells." (PMID 25884680, 2015). "We first examined whether there was evidence for eIF4E expression in untreated DLBCL tumor samples using a DLBCL TMA for IHC." (PMID 25839159, 2015). "eIF4E overexpression is considered to be a valuable prognostic marker in various tumor types." (PMID 25435943, 2015). "eIF4E is the main composition factor of eIF4F translation initiation complex, which binds with the 5’7-methyl guanosine (m7G) mRNA cap and influences the growth of tumor through modulating cap-dependent protein expression." (PMID 26317515, 2015). "Positive staining for eIF4E was found in the cytoplasm of the tumor cells." (PMID 25342548, 2014). "Thus, a signal loop involving eIF4E andαvβ6 probably exists to play a key role in tumor cellular growth and migration." (PMID 24839543, 2014). "From this point, we could speculate that, to some extent, the expression of eIF4E was related to tumor’s metastasis and progression." (PMID 24839543, 2014). "Moreover, an anti-tumor effect of targeted down-regulation of eIF-4E has been shown in several studies using diverse tumor xenograft models." (PMID 24086701, 2013). "EIF4E is a key factor in cap-dependent translation initiation (including several important oncoproteins such as c-Myc, cyclin D1, hypoxia-inducible factor 1, and Mcl-1) that controls tumor cell growth and survival." (PMID 23383345, 2013). "Conversely, activated Mnk1 promoted the onset of tumour development in a similar manner to eIF4E." (PMID 22392765, 2012). "Similarly, mice reconstituted with cells carrying the Ser209Ala mutant were defective in tumour development to a similar extent to the Trp56Ala mice, suggesting that phosphorylation of Ser209 is important for eIF4E-mediated tumourigenesis." (PMID 22392765, 2012). "Two tumor-promoting proteins regulated by EIF-4E—VEGF and cyclin D1—were also reduced." (PMID 22989709, 2012). "The studies have provided proof of concept that the deregulation of eIF4E-mediated translation initiation is an important step in oncogenic transformation and may contribute to tumour maintenance." (PMID 22392765, 2012). "Furthermore the reduction of eIF4E also appeared to prevent endothelial cell tube formation suggesting a possible role for eIF4E in tumor angiogenesis." (PMID 21378410, 2011). "Similarly, eIF4GI overexpression appears to phenocopy some of the oncogenic features of eIF4E: it too can drive transformation of mouse cell lines and increased expression has been found in some overlapping tumor tissues." (PMID 21378410, 2011). "However, higher pre-treatment eIF4E activity was significantly associated with dramatic post-treatment changes in expression of eIF4E and 4E-binding proteins, suggesting that eIF4E is further deregulated in these tumours in response to mTOR inhibition." (PMID 21320304, 2011). "As such, we can speculate that there may be tissue-specific requirements for the eIF4E oncogenic activity downstream of AKT hyperactivation in tumour development." (PMID 21772331, 2011).